HOXB13 (homeobox B13)
Diseases named in the same sentence as HOXB13 in open-access papers (continued):
Sharing a sentence is not in itself a finding about the gene and the disease.
neuroendocrine tumor (1 paper, 2025). "We further present evidence that the upregulation of HOXB13 in MPE (and in cauda equina neuroendocrine tumors) is likely due to differential HOXB13-associated CpG site methylation when compared to SP-EP." (PMID 40137996, 2025). "Similar to MPE, cauda equina neuroendocrine tumors with strong nuclear HOXB13 positivity showed low levels of cg01799458-BC21 methylation (mean methylated allele frequency: 10.5%, SD: 5.3%)." (PMID 40137996, 2025). "Our data, furthermore, show that differential DNA methylation of HOXB13 is a likely mechanism underlying the differential HOXB13 protein expression in MPE and cauda equina neuroendocrine tumors vs. SP-EP." (PMID 40137996, 2025). "In addition, 11/46 cases of histologically classified SP-EP (24.0%) also showed strong nuclear HOXB13 immunoreactivity, similar to the MPE and cauda equina neuroendocrine tumor cases." (PMID 40137996, 2025). "Among the non-ependymal spinal tumor types, only cauda equina neuroendocrine tumor (previously paraganglioma) demonstrated strong nuclear HOXB13 expression." (PMID 40137996, 2025). "In summary, the data reported in this study together with previous findings support that strong nuclear HOXB13 expression distinguishes MPE from SP-EP and SP-SE, as well as other spinal tumors except for cauda equina neuroendocrine tumor (previously paraganglioma)." (PMID 40137996, 2025).
Obesity (1 paper, 2025). Accumulation of substantial excess body fat. "Thus, we studied the impact of early-life or lifelong exposure to a high-fat diet (HFD) on PCa biomarkers [Homeobox B13 (HOXB13) and the Androgen Receptor (AR)] and their correlation with obesity-related markers." (PMID 40481981, 2025).
posterior fossa ependymoma (1 paper, 2025). A high grade ependymoma that is located within the posterior fossa. "On the other hand, none of the 10 SP-EP with either weak or absent nuclear HOXB13 expression, the 3 SP-SE with weak or negative nuclear HOXB13 expression, and the 4 HOXB13-negative spinal metastases of posterior fossa ependymoma was assigned to the MPE methylation class." (PMID 40137996, 2025).
rectal tumor (1 paper, 2025). "In clinical tumor samples, highlevels of HOXB13 gene transcripts are observed in prostateand rectal tumor tissues." (PMID 41164275, 2025).
spinal neoplasms (1 paper, 2025). "Here, we evaluated the diagnostic role of HOXB13 immunostaining in 143 spinal neoplasms, comprising 54 histologically classified myxopapillary ependymomas, 46 histologically classified spinal ependymomas, and various other tumor types." (PMID 40137996, 2025).
subependymoma (1 paper, 2010). Subependymoma is a rare and slow growing type of ependymoma, often presenting in middle-aged adults, found more commonly in men than in women, usually located in the fourth and lateral ventricles and manifesting with variable symptoms including headache, nausea, and loss of balance. "Immunoreactivity for HOXB13, NEFL and PDGFRα was strongest in MEPN and virtually absent in subependymoma." (PMID 19793339, 2010).
supratentorial ependymoma (1 paper, 2025). A high grade ependymoma that is located within the supratentorial brain. "A previous study also reported on weak HOXB13 expression in individual cases histologically diagnosed as MPE or supratentorial ependymoma; however, the results were not related to DNA methylation-based classification." (PMID 40137996, 2025).
tethered cord syndrome (1 paper, 2010). "Nine of 13 MEPN were positive for HOXB13, including a single case of incidental adult MEPN found in a filum terminale resected for tethered cord syndrome." (PMID 19793339, 2010).
tumor (128 papers, 2005 to 2026). "The role of HOXB13 in both development of the prostate gland and tumor progression indicates that mutations in HOXB13 drive oncogenesis through changes in transcriptional control over key regulatory pathways." (PMID 40433050, 2025). "HOXB13 germline variants were also shown to have an AR-independent role in PCa progression, through lipid accumulation that promotes cell motility and tumor metastasis." (PMID 40833121, 2025). "It is a molecular assay that examines the expression of 11 genes: seven genes associated with tumor proliferation and estrogen signaling (the Molecular Grade Index and HOXB13/IL17BR ratio) and four reference genes." (PMID 41149457, 2025). "Accordingly, HOXB13 loss results in an enhanced lipogenic program in PCa, which has been associated with tumor metastasis." (PMID 41277556, 2025). "This analysis revealed that ≈66% of tumor cells exhibited a loss of HOXB13 expression upon treatment." (PMID 40349174, 2025). "Although limited by small sample size, these findings suggest a possible link between the HOXB13 X285K variant and early tumor progression." (PMID 41188766, 2025). "Increased HOXB13 acetylation is a hallmark of tumor-specific super enhancers and genes associated with increased transcriptional activity and interacts with SWI/SNF chromatin remodeling complex." (PMID 38730575, 2024). "Low HOXB13 expression was significantly associated with muscle-invasive bladder cancer, higher tumor stage, tumor grade, and metastatic risk." (PMID 37627895, 2023). "Proteoglycans in cancer is the most enriched pathway associated with MEIS1 and HOXB13 inhibition, inducing tumor suppression and DCN, LUM, and TGFBR3, as well as regulating growth factor, migration, and invasion signaling through receptor tyrosine kinases." (PMID 36661515, 2023). "HOXB13 protein expression was significantly associated with tumor invasiveness (p ≤ 0.001), tumor stage (p ≤ 0.001), tumor grade (p = 0.001), and metastasis (p = 0.005)." (PMID 37627895, 2023). "Paradoxically, several studies have unveiled an intriguing association between elevated HOXB13 levels and the progression of tumor growth." (PMID 38068717, 2023). "HOXB13 binding sites overlap extensively with tumor-associated AR binding sites in clinical specimens, and transduction of HOXB13 in an immortalized normal prostate epithelial cell line is capable of reprogramming the AR cistrome." (PMID 36212399, 2022). "Deregulation of HOXB13 expression has been implicated in a variety of other human cancers, functioning as a tumor-promoting factor in some tumor types and a tumor-repressing factor in other tumor types." (PMID 33514011, 2021). "One novel pathway to understand tumor etiology and disease progression as well as develop new treatments is through HOXB13, which exhibits germline mutation in a subset of familial PrCa." (PMID 32553107, 2020). "This study examined 751 cases, 450 relatives and 355 controls to determine the contribution of this variant to PCa risk in Tasmania and investigated HOXB13 gene and protein expression in tumours from nine G84E heterozygote variant and 13 wild-type carriers." (PMID 29259341, 2017). "The oncogenic potential of HOXB13 mutations in phenotypic changes associated with tumor progression was explored by evaluating anchorage independent growth and invasion in vitro." (PMID 28050579, 2016). "The expression levels of the established cell models were similar to those found in normal prostate tissues and tumor samples, including the tumor P308T from a HOXB13 A128D mutation carrier." (PMID 28050579, 2016). "The significant associations of HOXB13 staining levels with various clinical, pathological and molecular tumor parameters indicate, that our measurements reflect true and biologically relevant expression differences between cancers." (PMID 25825985, 2015).
tumor (continued). "HOXB13 immunostaining was linked to advanced pathological tumor stage, high Gleason grade, and lymph node metastasis (p < 0.0001 each) in subsets of both ERG-negative and ERG-positive cancers." (PMID 25825985, 2015). "It is also conceivable that loss of HOXB13 will lead tumour development and/or tumour progression to advanced form." (PMID 15928669, 2005). "Pharmacological inhibitors of p300/CBP abolished HOXB13-loss-induced tumor metastasis." (PMID 41277556, 2025). "Next, we evaluated whether p300/CBP inhibition can attenuate HOXB13-loss-induced tumor metastasis in vivo." (PMID 41277556, 2025). "Similarly, in lung cancer, HOXB13 is markedly overexpressed and is closely associated with tumor aggressiveness and unfavorable clinical outcomes." (PMID 41023726, 2025). "In addition, HOXB13 protein localization was significantly associated with tumor invasiveness (p ≤ 0.001), tumor stage (p ≤ 0.001), tumor grade (p = 0.032), and metastasis (p = 0.001)." (PMID 37627895, 2023). "Similarly, HCC tissues exhibit elevated expression of HOXB13 and AR compared to normal tissues, implying their tumour‐associated properties and clinical relevance." (PMID 38093528, 2023). "It is worth noting that HOXB13 expression has a well-documented association with the Wnt signaling pathway, effectively amplifying the intricate web of regulatory interactions that lead to the augmentation of tumor invasion and metastasis." (PMID 38068717, 2023). "However, co-transduction of FOXA1 and HOXB13 together ultimately results in the most dramatic shift in the AR cistrome away from normal prostate-associated AR binding sites towards tumor-associated AR binding sites." (PMID 36212399, 2022). "Within the context of HOXB13-associated binding partners, HOXB13 may provide specificity for DNA binding and subsequent tumor progression or repression." (PMID 33514011, 2021). "While the overexpression of FOXA1 and HOXB13 pushes AR cistrome to a more tumor-like profile, pioneering activity of GATA2 allows AR to bind to enhancers of metastasis and treatment resistance associated genes, thereby contributing to PCa progression." (PMID 40833121, 2025). "The functional roles of HOXB13 in driving tumorigenesis are likely tumor-specific, with both oncogenic or tumor-suppressive functions being reported." (PMID 40137996, 2025). "Analysis of clinical samples revealed that HOXB13 expression is reduced in metastatic hormone-sensitive PCa compared with matched primary tumors, further supporting its role in tumor metastasis." (PMID 41277556, 2025). "In vivo, the sh-HOXB13 group exhibited reduced tumor mass, volume and lung metastatic nodules compared to the sh-NC group." (PMID 41023726, 2025). "Due to the inability to isolate the tumor in this model (i.e., the tumor is diffused in the liver tissue), we restricted our analysis to immunostaining for HoxB13 in the liver sections with metastatic PC‐3 cells." (PMID 40349174, 2025). "However, the mechanisms linking HOXB13 loss to tumor metastasis remain unclear." (PMID 41277556, 2025). "In vivo, NPC cells transfected with sh-HOXB13 were injected into nude mice, after which tumor volume and mass were measured, and lung metastases were analyzed using hematoxylin and eosin (H&E) staining." (PMID 41023726, 2025). "In contrast, only 1 mouse in the control group developed detectable metastatic tumors (in the lung and prostate), confirming that HOXB13 KD increased tumor metastasis (week 7)." (PMID 41277556, 2025). "Tumor development was monitored, and the results showed that both tumor volume and tumor weight were significantly reduced in the sh-HOXB13 group compared to the sh-NC group." (PMID 41023726, 2025). "Known founder mutations were identified in tumor profiling reports of seven unique cases (8.4%; 7/83), including CHEK2 (I157T, n = 1), HOXB13 (G84E, n = 2) and MUTYH (G368D, n = 2 and Y151C, n = 2)." (PMID 39885482, 2025).
tumor (continued). "IVIS imaging revealed that more tumor cells metastasized to distant organs, such as the liver, lung, rib, hind leg, and prostate, in the HOXB13-KD group compared with the control and CCS1477-treated mice." (PMID 41277556, 2025). "In cervical cancer, HOXB13 has been shown to activate the NF-κB signaling pathway, thereby promoting tumor growth." (PMID 41023726, 2025). "Research has identified specific members of the HOX family with tumor-suppressive capabilities; for instance, HOXB13 has been characterized as a tumor suppressor." (PMID 39138733, 2024). "This trend was maintained between AR and HOXB13, although slightly reduced in tumor (normal prostate: r = 0.804, P = <0.0001; tumor: r = 0.598, P = 0.006), and between PSMA and AR (normal prostate: r = 0.878, P < 0.0001; tumor: r = 0.458, P = 0.048)." (PMID 38936974, 2024). "In total, 13 patients (13%) carried a P/LP variant in a known autosomal dominant tumor predisposition gene: APC (n = 1), BRCA2 (n = 2), CHEK2 (n = 4), DICER1 (n = 4), HOXB13 (n = 1), and MITF (n = 1)." (PMID 38415346, 2024). "We investigated the correlation between HOXB13 and six tumor immune-infiltrating cells using the TIMER database." (PMID 38792899, 2024). "We used TIMER to examine RNA sequencing data from the TCGA and evaluated HOXB13 expression levels in specific tumor types." (PMID 38792899, 2024). "Here, we found the overexpression of FOXA1 and HOXB13 alone, or in combination, to markedly shift the AR cistrome away from full AREs (normal-like) towards chimeric AR half elements in the tumor-like state." (PMID 39251788, 2024). "In total, 13 of 97 patients (13%) carried a germline (likely) pathogenic variant in a well-known tumor predisposition gene: APC (n = 1), BRCA2 (n = 2), CHEK2 (n = 4), DICER1 (n = 4), HOXB13 (n = 1), and MITF (n = 1)." (PMID 38415346, 2024). "Functionally, this single-site mutation at HOXB13 increases sensitivity to ENZ and inhibits CRPC xenograft tumor growth." (PMID 38730575, 2024). "Induced expression of HOXB13 inhibited tumor cell proliferation and induced apoptosis, suggesting that HOXB13 acts as a tumor suppressor gene in these types of cancers." (PMID 37627895, 2023). "The overexpression of HOXB13 was shown to promote tumor cell proliferation and inhibit apoptosis, suggesting an oncogenic role for HOXB13 in these cancers." (PMID 37627895, 2023). "Elevated expression levels of HOXB13 have been shown in CRPC tumours when compared to hormone-sensitive tumours, and it has been demonstrated that HOXB13 interacts with the DBD of the AR, regulating the transcriptional activity of genes containing AREs." (PMID 36937454, 2023). "This surge in HOXB13 expression is intricately tied to the facilitation of tumor cell invasion and the subsequent orchestration of metastatic events when examined in vitro." (PMID 38068717, 2023). "HOXB13 suppresses wnt/β‐catenin signalling in colon cancer, hence exhibiting a tumour suppressor function in this context, but does so through inhibiting transcription of the TCF4 gene (the product of which encodes a cofactor for β‐catenin)." (PMID 35080776, 2022). "Hormone- and context-dependent activities of these master regulators further involve pioneer factors that mediate AR-driven transcriptional programming; GATA2, FOXA1, and HOXB13 drive lineage-specific gene expression that is critical for tumor development." (PMID 36181613, 2022). "FTO can decrease HOXB13 mRNA decay and increase HOXB13 protein expression, promoting Wnt signaling pathway activation and the expression of downstream proteins, leading to tumor metastasis and invasion." (PMID 35813486, 2022). "The AR-V7-regulated transcriptome varies a lot across CRPC patients but genes involved in tumor progression and additionally coregulated by HOXB13 are often detected." (PMID 35682963, 2022).
tumor (continued). "FOXA1 is essential for AR reprogramming towards a cancerous phenotype and its overexpression, together with that of HOXB13, leads to a shift in the AR cistrome in an immortalized prostate epithelial cell line towards a tumor-like phenotype." (PMID 35682963, 2022). "In both GEMM and ODT models, tumour cells in the metastatic foci displayed expression of Hoxb13, low levels of AR and K8 but high levels of Syp and Ncam, suggesting the prostatic origin and stable neuroendocrine signature of these metastatic tumour foci." (PMID 34021647, 2021). "Despite this loss, high-grade tumours exhibit an enrichment for FOXA1, HOXB13 and CDX2 transcription factor binding sites, indicating a shared trans-regulatory programme." (PMID 34911933, 2021). "Integration of ChIP-seq and RNA-seq data revealed direct and HOXB13-dependent regulation of proteoglycans including decorin (DCN) as a mechanism of MEIS1-driven tumor suppression." (PMID 32553107, 2020). "Studies geared specifically towards specific tumor location, have identified suppression of HOXB13 within distal tumors and upregulation within proximal tumors, consistent with our current analysis." (PMID 32293332, 2020). "In this study, we describe that MEIS1—cooperatively with HOXB13—is responsible for maintaining expression of secreted, tumor-suppressive proteoglycans such as DCN." (PMID 32553107, 2020). "The interdependence of MEIS1 and HOXB13 to promote tumor suppression implies that changes to either factor enable the other factor to pair with an oncogenic driver." (PMID 32553107, 2020). "Our studies revealed a tumor suppressive role of Suv39h1 in MLL-r AML that is partially mediated by inactivation of Hoxb13 and Six1, as well as reversion of Hoxa9/Meis1 downstream transcriptomes." (PMID 33037410, 2020). "Our study provides a compelling argument for regulation of proteoglycans by MEIS1 and HOXB13 as a mechanism for MEIS-driven tumor suppression in PrCa." (PMID 32553107, 2020). "The HOXB13-dependency of MEIS1 tumor suppressive function in PrCa cells was further demonstrated with the analyses of cell migration phenotypes." (PMID 32553107, 2020). "In our study, we show that HOXC4 and HOXC6 colocalize with HOXB13, which is present at high levels in both normal and tumor prostate tissue." (PMID 32012197, 2020). "In the present study, gene expression information from 5 GEO datasets and clinical tumor tissues showed that HOXB13 is differentially expressed in RCC and LCC and has prognostic significance in only RCC." (PMID 31815008, 2019). "Here, we used a public genomic database to identify differentially expressed genes (DEGs) according to tumor location and found that HOXB13 is an RCC-specific tumor suppressor gene." (PMID 31815008, 2019). "More intense Ki-67 staining was observed in tumor cells with low HOXB13 expression compared to control cells (32.5 ± 1.5 vs 22.5 ± 0.5%, respectively, P = 0.024)." (PMID 31815008, 2019). "Patients with high HOXB13 expression had low C-myc expression, although C-myc is known to be expressed at high levels in tumor tissues." (PMID 31815008, 2019). "In conclusion, the current study is the first to demonstrate that HOXB13 has a tumor-suppressive effect in RCC." (PMID 31815008, 2019). "HoxB13 expression is significantly higher in tumor (68.2%) than in adjacent non-tumor tissue (22.4%)." (PMID 31137902, 2019). "Further studies in animal models based on specific tumor locations can provide more reliable evidence to support the role of HOXB13 in RCC." (PMID 31815008, 2019). "In 33 RCC patients, HOXB13 expression in normal samples was higher than that in tumor samples (8.16 ± 0.44 vs 4.82 ± 0.41, respectively, P < 0.0001)." (PMID 31815008, 2019). "Collectively, our results indicate that HOXB13 promotes metastasis of PCs by coordinated regulation of mitotic kinases and blockade of a putative tumor suppressor gene." (PMID 31273254, 2019).